MAVS (mitochondrial antiviral signaling protein)
Diseases named in the same sentence as MAVS in open-access papers (continued):
Sharing a sentence is not in itself a finding about the gene and the disease.
tumor (continued). "Alterations in the expression of DDX58, MAVS, C6orf150, TMEM173, IKBKE, TBK1 and IRF3 were analyzed across different tumor samples using cBioPortal." (PMID 38817870, 2024). "Furthermore, based on the recent evidence showing that STING pathways in cancer cells may be also involved in cell death induction, we believe that an effective delivery of STING and MAVS through PBMC-EXs may enhance the suppression of tumor growth and activate an antitumor immunity response." (PMID 39335123, 2024). "Consistent with this, simultaneous abrogation of MDA5 and cGAS, RIG-I and cGAS, or MAVS and STING impaired shPhf8-induced anti-tumor effects in vivo." (PMID 37454216, 2023). "Hypomethylation of ERV genes in tumor cells can result in transcription and formation of dsRNA that are sensed by cytosolic pathogen-sensing, pattern-recognition receptors such as MDA5/MAVS." (PMID 36227698, 2022). "Lactate is able to bind to MAVS and disrupt MAVS-RIG-I interaction, thereby impairing anti-tumor immunity." (PMID 36510194, 2022). "These exosomes deliver various types of non-coding RNAs to tumor cells, resulting in the activation of the RIG-I/MAVS pathway, which eventually induce the IRDS signature in tumor cells." (PMID 27034163, 2016). "Three activated UPRs associated with immune activation were unique to CPA/6d-treated GL261(B6) tumors: EIF2AK2, IFNL1 and MAVS, while the two activated UPRs specific to GL261(scid) tumor responses, DMD and SPARC, have glial cell-related functions:." (PMID 27515027, 2016). "Furthermore, E5 has been found to bind directly to the mitochondrial antiviral signaling protein (MAVS) and stimulator of interferon genes (STING) proteins, which are key proteins that block their activity and hamper the immune response against tumor cells." (PMID 39772271, 2024). "Depletion of MAVS led to a significant tumor regrowth following IR with no apparent effect on untreated tumors." (PMID 27034163, 2016). "Targeting the LGP2/RIG-I/MAVS/IFN-beta pathway may provide new strategies for radioprotection after exposure to total body or abdominal irradiation, as well as tumor sensitization to IR." (PMID 27034163, 2016). "However, the mechanisms of deubiquitination of MAVS and its role in anti-tumor immunity are not fully understood." (PMID 40016186, 2025). "It has been shown that the upregulated hub MMRG genes BCL2, MAVS, FKBP8, NBR1, and SLC25A6 and their products can participate in regulating drug resistance of tumour cells and the antitumour immune response and may be associated with the activation of inflammatory signalling pathways." (PMID 41463291, 2025). "Moreover, for that, E5 is capable of suppressing the IFN I pathway by interacting with and binding to Mitochondrial Antiviral-Signaling Protein (MAVS) and Stimulator of IFN Genes (STING), with evidence of direct suppression of E5 on the activity of STING agonists in two mouse tumor challenge models." (PMID 40284955, 2025). "Therefore, a change in MAVS expression (because of ADAR1 editing) within the tumor seems to be a strong corollary of ISG/NF-κB signaling and presumably of downstream interferon production and tumor survival signaling, respectively." (PMID 37255666, 2023). "Initially, we examined the expression levels of key genes within the innate immune pathway, namely DDX58, MAVS, C6orf150, TMEM173, IKBKE, TBK1 and IRF3, across diverse tumor and non-tumor tissues." (PMID 38817870, 2024). "Our findings indicated that DDX58, MAVS, C6orf150, IKBKE, TBK1, and IRF3 expression were not significantly correlated with tumor purity." (PMID 38817870, 2024). "N-MYC suppressed tumor cell–intrinsic STING and RIG-I–like receptor signaling by inhibiting in vitro oligomerization of STING and MAVS, independent of transcriptional repression." (PMID 38748789, 2024).
tumor (continued). "We further show in vitro that N-MYC suppresses STING and RLR signaling in a tumor cell–intrinsic fashion by inhibiting oligomerization of STING and MAVS (mitochondrial antiviral-signaling protein) independent of transcriptional repression." (PMID 38748789, 2024). "Our results revealed that the promoter methylation levels of DDX58, MAVS, TMEM173, and IRF3 did not exhibit significant differences between normal and tumor samples." (PMID 38817870, 2024). "Therapy-induced tumor rejection was dependent on CD4+ and CD8+ T cells, but not on NK or B cells, and relied on intact IFN and mitochondrial antiviral signaling protein (MAVS) signaling in the host." (PMID 31740809, 2020). "Importantly, we found that DS-induced IFN-I activation in tumor cells is dependent on TBK1; silencing TBK1, but not MAVS, STING, or MyD88, abolished DS-mediated IFN-I activation." (PMID 40625660, 2025). "We did not observe diminished expression of other immune sensors MAVS and MyD88 or downstream components of these immune pathways TBK1 and IRF3; suggesting that targeting of STING-specific immune responses may be an important strategy to facilitate tumor progression in HPV+ HNSCCs." (PMID 38147007, 2024).
cancer (52 papers, 2011 to 2025). A tumor composed of atypical neoplastic, often pleomorphic cells that invade other tissues. "Recent studies demonstrate that MAVS is implicated in responses to bacterial and parasitic infections, autoimmune diseases, cancer advancement, kidney diseases and cardiovascular diseases." (PMID 40040697, 2025). "The data presented in this study broaden these findings, as we show IFN signaling in STING-deficient cancers is also possible through mtRNA’s activation of MAVS during CICD." (PMID 36918588, 2023). "MAVS signaling has recently been implicated in type I IFN production after irradiation of cancer cells." (PMID 33238631, 2020). "Distinct from the cell lethality phenotype, loss of ADAR1 primes cancer cell lines to produce IFN-β in response to IFN-β stimulation in a MDA5/MAVS-dependent manner." (PMID 30575730, 2018). "The surprising activation of MAVS/RIG-I signaling by AURKi might represent a vulnerability in STING signaling deficient cancers." (PMID 38358346, 2024). "From this report, we assume that the transfer of MAVS-deficient DC instead of wild-type DC might induce robust anti-cancer immunity in CIRT-receiving patients with cancer." (PMID 38474078, 2024). "Our results after MAVS knockdown suggest that either RIG-I or MDA5 is involved in the CXCL10 secretion by cancer cells and that the TLR3 pathway contributes at least as much to CXCL10 secretion as the MAVS pathway." (PMID 40029556, 2025). "Activation of the RIG-I/IFIH1/MAVS pathway and de-repression of ERVs were observed in cancer, aging, autoimmune, and neurodegenerative diseases." (PMID 38383514, 2024). "Except for the immune checkpoints, the RIG-I-like receptors/MAVS signaling pathway is emerging as another target for cancer immunotherapy." (PMID 38233872, 2024). "Mechanistically, we find that 4-OI suppresses antiviral immunity in cancer cells through the modification of cysteine residues in MAVS and IKKβ independently of the NRF2/KEAP1 axis." (PMID 38750019, 2024). "In our previous study, we found that Cdk2−/− cancer cells also had increased intracellular levels of endogenous retroviral double-stranded RNA and hyper-activation of interferon response through the MAVS-dependent signaling pathway." (PMID 37833461, 2023). "In a separate study, we found that Cdk2−/− cancer cells had increased intracellular levels of endogenous retroviral double-stranded RNA and hyper-activation of interferon response through the MAVS-dependent signaling pathway." (PMID 37833461, 2023). "In summary, our results not only shed light on the mechanism by which WDR77 inhibits prion-like aggregation of MAVS to suppress IFN-β induction in antiviral immune response but also provide insights into the clinical relevance of WDR77 in cancer biology." (PMID 37563140, 2023). "Among some genes associated with disease and immunity, DOK2 and TIMM17A are related to cancer, LMODI is linked to hypoperistalsis, MAVS is essential for virus-activated signaling pathways, and DOCK8 is linked to humoral immunity." (PMID 36139261, 2022). "Our results supported the possibility that cancers with high MAVS expression have poor prognosis due to a decrease in the immune response regulated by T cells." (PMID 34722508, 2021). "Together, these data support the notion that ADAR knockout can trigger the activation of the IFN-I pathway (MDA5/MAVS-dependent) and the induction of cell lethality (MDA5/MAVS-independent) through distinct upstream mechanisms in cancer cell lines." (PMID 30575730, 2018). "Additionally, MOMP caused by BAX/BAK can lead to the release of mtDNA and mt-dsRNA into the cytosol, activating the cGAS/STING and RIG-I/MAVS pathways within cancer cells, which elicits the secretion of type I IFN cytokines for ICD induction." (PMID 41304887, 2025). "The ability for NLRX1 to inhibit MAVS and the subsequent IFN-I signaling has also been implicated in persistent Hepatitis C (HCV) infections, which can increase the risk for many types of cancer." (PMID 37342194, 2023).
cancer (continued). "It has also been suggested that MAVS is highly related to apoptosis in cancer cells." (PMID 34722508, 2021). "Thus, in contrast to inhibition of oncogene signaling, direct RIG-I activation leads to a MAVS-dependent induction of cytokine secretion and cell killing across cancer cells." (PMID 34535668, 2021). "Thus, induction of a viral mimicry state in cancer cells by 5-aza-2′-deoxycytidine is dependent on the activation of MAD5/MAVS/IRF7 axis and type III IFNs." (PMID 29706891, 2018). "In this minireview, we will highlight the newest insights from preclinical studies demonstrating the relevance of manipulating the cGAS-STING and RLRs-MAVS signaling pathways for cancer treatment and how these pathways are currently being targeted pharmacologically." (PMID 29686682, 2018). "Suppression of MAVS conferred radioresistance in normal and cancer cells." (PMID 27034163, 2016). "Recent data suggested that TNF-related apoptosis-inducing ligand (TRAIL) and Noxa represented promising target molecules for cancer cell-selective apoptosis when the retinoic acid–inducible gene I/mitochondrial antiviral signaling protein (RIG-I/MAVS) signaling pathway was activated." (PMID 24007528, 2013). "Recent studies demonstrated that the cancer cell type and species (human versus mouse) contribute to the relative contributions of the cGAS/STING and POLIII/RIG-I/MAVS nucleic acid–sensing pathways in radiation-induced T1IFN expression." (PMID 38376927, 2024). "TBK1 functions as a central node for several innate immune pathways, including the POLIII/RIG-I/MAVS pathway, which is required for radiation-induced T1IFN expression in some cancer types." (PMID 38376927, 2024). "Recently, however, the mitochondrial antiviral signaling protein (MAVS), an important signaling molecule in innate immunity, was shown to downregulate the anti-cancer immunity of DCs." (PMID 38474078, 2024). "Mutations or abnormal expression levels of specific genes in the RLR signaling pathway, such as MAVS, TBK1, and IRF3, can lead to changes in the immune signaling pathway, resulting in a decreased ability of immune cells to recognize and clear malignant tumors." (PMID 38099311, 2023). "Treatment of high-grade glioma with either DNMTi or HDACi has been shown to more strongly promote MAVS-dependent induction of IFN and IFN-stimulated genes in H3.3K27M cancers than H3.3 wild-type cancers." (PMID 38071304, 2023). "To determine which adaptor is necessary for RIG-I to activate downstream signaling pathways in cancer cells, we studied the expression of TRIF, MAVS, and STING in PANC-1 cells." (PMID 33490069, 2020). "The ability of poly(I:C) to suppress cancer cell proliferation was unaffected by MAVS or TICAM-1 knockdown (data not shown)." (PMID 40029556, 2025). "It was reported that MAVS is necessary for IFN-beta induction and interferon-stimulated gene expression in the response to IR and suppression of MAVS conferred radioresistance in normal and cancer cells." (PMID 32190169, 2020). "Furthermore, when MAD5/MAVS/IRF7 axis is genetically inactivated, cancer cell lines become insensitive to 5-aza-2′-deoxycytidine treatment." (PMID 29706891, 2018). "This may suggest that MAVS over-expression offers another unidentified strategy by which CLL cells resist apoptosis, or fulfil another function with advantage to cancer cells." (PMID 27078856, 2016). "In contrast, non-canonical MAVS signaling alleviates DC-mediated anti-cancer immunity." (PMID 38474078, 2024). "The results showed that TLR3, TRIF, RIG-I, MDA5, LGP2, and MAVS, which were reported to be expressed in the A549 cell line, were expressed in all these cells lines at both the mRNA and protein levels, indicating that the TLR–TRIF and RLR–MAVS pathways are constitutively intact in all cancer cells." (PMID 33490069, 2020).
cancer (continued). "Moreover, we demonstrated that HVJ-E RNA fragment-dependent activation of the cytoplasmic RNA receptor retinoic acid-inducible gene-I (RIG-I) and mitochondrial antiviral signaling protein (MAVS) activates the upregulation of TRAIL and Noxa, which enables HVJ-E-mediated cancer-selective apoptosis." (PMID 27145280, 2016). "Furthermore, HVJ-E could also induce cancer-selective apoptosis via the upregulation of TRAIL and Noxa downstream of the RIG-I/MAVS pathway." (PMID 24007528, 2013). "As for other genes involved in dsDNA/dsRNA/ssRNA sensing like CGAS, RIG-I, MAVS, DDX41, and IFI16, whose expression in either cancer cells or other cell types, were not significantly impacted by redox status of any cell types." (PMID 41378285, 2025). "However, our studies showed that only inactivation of STING but not MAVS, could reverse the higher levels of ISG expression in Cdk4−/− and Cdk6−/− cancer cells." (PMID 37833461, 2023).
bacterial infection (5 papers, 2012 to 2021). "Alternative pathways leading to IFN production downstream of bacterial infection include those linked to the cytosolic nucleic acid receptors MAVS and STING." (PMID 33684179, 2021). "Since then, the number of PRRs that link bacterial infection with IFN production has grown to include many cytosolic receptors including MAVS and STING." (PMID 33684179, 2021). "Our findings that ICAM-1 expression is diminished in BMMs that lack RIG-I or MAVS expression following an M. avium infection suggest a link between RNA sensing pathways and an immune response to this bacterial infection." (PMID 32463840, 2020). "Likewise, activation of MAVS has been shown to occur during intracellular bacterial infection, likely through the recognition of bacterial mRNA by RIG-I." (PMID 33684179, 2021). "However, whether the activation of the RIG-I/MAVS RNA sensor pathway stimulates other cellular responses following a bacterial infection remains undefined." (PMID 32463840, 2020). "Bacterial infection can lead to the production of IFNs downstream of multiple pattern recognition receptors (PRRs) found on macrophages, including Toll-like receptors (TLRs), RIG-I-like receptors (RLRs), and other cytosolic nucleic acid sensors such as MAVS and STING." (PMID 33684179, 2021). "It is also notable that expression of TNF-α mRNAs was also drastically suppressed in all the KO MEFs upon bacterial infection, suggesting a significant role of RIG-I/MAVS and STING signaling pathways in non-phagocytic host cells." (PMID 30233599, 2018).
cardiovascular diseases (3 papers, 2023 to 2025). "In addition to classical interactors and PTMs, MAVS activity is modulated by various microRNAs and mitochondria-associated proteins, many of which also play important roles in cardiovascular diseases." (PMID 40842475, 2025). "We further highlight the involvement of MAVS in the development of cardiovascular diseases through its participation in innate immune signaling and mitochondrial dynamics." (PMID 40842475, 2025). "By systematically summarizing the research progress of MAVS in the cardiovascular system, we aim to offer new insights into the prevention and treatment of cardiovascular diseases in the future." (PMID 40842475, 2025). "Emerging evidence indicates that MAVS is not only essential in antiviral defense but also contributes significantly to the pathogenesis of various diseases, notably cardiovascular diseases." (PMID 40842475, 2025). "This review aims to summarize the mechanism of action of MAVS in cardiovascular diseases and its potential clinical application value." (PMID 40842475, 2025). "Emerging evidence suggests that MAVS is also closely related to the pathogenesis of various cardiovascular diseases." (PMID 40842475, 2025). "These insights aim to deepen the understanding of MAVS as a potential biomarker and therapeutic target, offering novel perspectives for the prevention, diagnosis, and immunotherapeutic intervention of cardiovascular diseases." (PMID 40842475, 2025). "Therefore, understanding the molecular structure and biological function of MAVS not only aids in revealing its role in innate immunity but also provides a foundation for exploring its potential role in cardiovascular diseases." (PMID 40842475, 2025). "Here is the summary of PTMs that regulate MAVS or participate in cardiovascular diseases." (PMID 40842475, 2025). "Overall, the investigation of the close association between MAVS and the NLRP3 inflammasome in cardiovascular diseases provides us with deeper insights into the immune mechanisms underlying these conditions, while also offering potential drugs targeted NLRP3 for future therapeutic strategies." (PMID 40040697, 2025). "Therefore, the method to manipulate PTMs of MAVS could be a new direction for cardiovascular disease treatments." (PMID 40842475, 2025). "Although the function of MAVS in antiviral immune responses has been extensively studied, the significant role it plays in inflammatory response, apoptosis, and mitochondrial homeostasis has gradually drawn attention to the role of MAVS in cardiovascular diseases." (PMID 40842475, 2025). "Given the diverse and complex mechanism of the pathogenesis of cardiovascular diseases, when MAVS is absent, it will damage mitochondrial function, increase oxidative stress, and lead to the deterioration of the disease." (PMID 40842475, 2025).
immune diseases (2 papers, 2016 to 2021). "In any case, we suggest that such MAVS variations may result in serious immune diseases, especially in infections." (PMID 26954674, 2016).
infectious disease (2 papers, 2016 to 2026). A disorder directly resulting from the presence and activity of a microbial, viral, or parasitic agent in humans. "Therefore, we initially thought that variants in the MAVS gene should result in dysfunction of the innate immune system, especially in the infectious diseases due to the gene’s crucial role in antiviral signalling." (PMID 26954674, 2016). "We speculated that genetic variation of MAVS may result in susceptibility to infectious diseases." (PMID 26954674, 2016). "Therefore, we speculate that variations in the MAVS gene may result in susceptibility to infectious diseases." (PMID 26954674, 2016).